SOD1 (superoxide dismutase 1)
Diseases named in the same sentence as SOD1 in open-access papers (continued):
Sharing a sentence is not in itself a finding about the gene and the disease.
tumor (389 papers, 1983 to 2026). "Some studies have shown that increased SOD1 levels are associated with increasing tumor activity in the lung and breast." (PMID 40244057, 2025). "We explain this result by the fact that CuMVs can modulate ROS production and the expression of superoxide dismutase (SOD1) in recipient macrophages, thus preventing the transition of M2 macrophages into TAMs (tumor-associated macrophages)." (PMID 41471070, 2025). "The present study provides important insights into the role of CHI3L1 in the regulation of ER stress associated UPR function and apoptosis, as well as the SOD1 dependent regulation of tumor growth." (PMID 37215572, 2023). "The levels of cytochrome c and SOD1 significantly increased in tumor associated mammary pads in RD-fed mice compared to HFD-fed mice at 1 and 5 wpi." (PMID 36675341, 2023). "COMMD1 causes tumor apoptosis in lung cancer by suppressing SOD1 expression, and in neuroblastoma, elevated nuclear expression of COMMD1 inhibits cyclin D1 expression, G1/S transition, and tumor cell proliferation." (PMID 34493238, 2021). "To evaluate the consequences of SOD1 loss in vivo, we used a nude mouse tumour model and administered 5-8F-shCon or 5-8F-shSOD1 cells and CNE2-shCon or CNE2-shSOD1 cells via subcutaneous injections into the flank." (PMID 29891006, 2018). "SOD1 associates cell survival and tumor growth in the tumor microenvironment." (PMID 37215572, 2023). "In this experiment, tumor development led to a reduced expression of antioxidant enzymes (gpx and sod1) and the detoxification enzyme gst, along with an increased expression of transcription factors related to inflammatory activity such as IL-1ß." (PMID 40284221, 2025). "The RT‐qPCR analysis of mouse tumor tissues revealed a concentration‐dependent decrease in SOD1 mRNA expression with increasing RBMD (Student’s t‐test, p < 0.05)." (PMID 41498040, 2025). "Inhibiting SOD1 resulted in a significant reduction in tumor proliferation, particularly evident in samples treated with LCS-1." (PMID 39123408, 2024). "In starved tumor regions, mTORC1 is physiologically inhibited leading to a dephosphorylation and consecutive activation of SOD1 enhancing the cellular redox defense capacity." (PMID 39187509, 2024). "Our results indicate that activation of SOD1 contributes to mTORC1 inhibition-mediated protective effects in the tumor microenvironment." (PMID 39187509, 2024). "The mentioned research confirms that SOD1 plays a role in tumor cell proliferation and hence represents a promising target for anti-tumor chemical compounds." (PMID 39123408, 2024). "In starved tumor regions mTORC1 is physiologically inhibited leading to a dephosphorylation and activation of SOD1 enhancing the cellular redox defense capacity." (PMID 39187509, 2024). "SOD1 mediates adaptation of GB cells to stress conditions in the tumor microenvironment in a mTORC1-dependent manner." (PMID 39187509, 2024). "Due to its high antioxidant activity and its direct control over the cellular ROS levels, SOD1 plays a crucial role in enabling the survival of tumor cells in a hypoxic tumor environment." (PMID 39187509, 2024). "A correlation pattern similar to that observed in cell lines was also observed in patient tumour samples, with an even stronger correlation between HBx and SOD1 expression (R2 = 0.99, p < 0.001)." (PMID 39034442, 2024).
tumor (continued). "Regarding the involvement of this protein in oncological pathogenesis, recent studies have shown that SOD1 is altered and overexpressed in tumors, and it appears to be able to promote the metastasis of tumor masses." (PMID 39123408, 2024). "SOD1 is more than an antioxidant enzyme; its inhibition by TM contributes to attenuating angiogenesis and tumor cell proliferation." (PMID 37365216, 2023). "The same cell line pair showed consistently increased (p > 0.001) SOD1 mRNA while a notable 1.9-fold increase in protein levels in vivo in four independent tumour quadrants." (PMID 37582934, 2023). "In a further way, copper can also promote the synthesis of FGF-1 through ATOX1 and superoxide dismutase 1 (SOD1) to affect vascular endothelial function, while increasing the invasive and metastatic capacity of tumor cells by activating lysyl oxidase (LOX)." (PMID 37476384, 2023). "The level of SOD1 protein was also significantly increased in lung tissues from metastatic and tumor sites of CHI3L1 KO mice, and the immune histochemical staining result confirmed this." (PMID 37215572, 2023). "For example, mutations in the SOD1 gene are associated with oxidative stress, and mutations in the LOXL2 gene are associated with tumor proliferation and invasion." (PMID 37886979, 2023). "SOD1 silencing was found to augment cisplatin-induced cytotoxicity resulting in considerable tumour growth inhibition in cisplatin-sensitive A2780 and cisplatin-resistant A2780DDP subcutaneous mouse xenografts." (PMID 37582934, 2023). "We found that metastasis presented lower SOD1 expression than the primary tumor, and patients with low expression of the SOD1 gene in the metastasis had worse EFS." (PMID 36982681, 2023). "Studies have shown that SOD1 can be widely expressed in cells, down-regulating the peroxides in tumor cells to extremely low levels, thereby leading to imbalance of energy metabolism in tumor cells and eventually resulting in cell death." (PMID 37256172, 2023). "The Caveolin-1(Cav1) and Superoxide Dismutase 1(SOD1) were supposed to as potential tumor suppressor and oncogene respectively." (PMID 36263135, 2022). "It acts as a tumor suppressor through upregulation of ROS levels and downregulation of SOD1 (a superoxide dismutase 1) activity and phosphorylation of the SOD1 downstream pathway PI3K/AKT." (PMID 36313435, 2022). "Stressed tumor cells therefore have a real interest for their survival in using the key enzyme, SOD1." (PMID 35918659, 2022). "Activation of PPARD has also been associated with the increased expression of both SOD1 and SOD2, which are linked with tumor progression and migration in AFG1-induced LA." (PMID 35342393, 2022). "We show that inhibiting both DGAT1 and superoxide dismutase 1 profoundly suppress tumor growth through eliciting intolerable oxidative stress." (PMID 35732120, 2022). "We next assessed the impact of combining inhibition of DGAT1 and SOD1 on tumor growth by using not only the BRAFV600E-mutant A375 xenograft model but also an NRASQ61R-mutant MM485 xenograft model." (PMID 35732120, 2022). "Strikingly, combined DGAT1 and SOD1 inhibition led to a profound reduction in tumor growth, with most animals demonstrating tumor regression in the MM485 xenograft model." (PMID 35732120, 2022). "In MCF-7-xenograft tumour nude mice and immunosuppressive mice, 30 mg/kg Phy treatment inhibited tumour growth from the 8th day, and reduced Bcl-2 and Bcl-xL >50%, HO-1 and SOD-1 > 70% in tumour tissues of immunosuppressive mice." (PMID 33715588, 2021). "Nonetheless, the expression of the three other enzymes, SOD1, Ref-1 and Trx were related to the tumor size." (PMID 34785721, 2021). "Sod1 knockout markedly reduces tumor burden in vivo and blocks growth of KRAS mutant NSCLC cells in vitro." (PMID 33859191, 2021).
tumor (continued). "A disturbance of its expression is associated with various cancers such as hepatocellular carcinoma, and overexpression of SOD1 promotes tumor growth in lung cancer cells and reduce apoptosis." (PMID 34568365, 2021). "Comparing tumor burden between 4 and 6 weeks after Sod1 knockout, the increase of tumor burden in Sod1−/− KP mice was much smaller than that of Sod1+/+ KP." (PMID 33859191, 2021). "High cytoplasmic expression of Trx (p < 0.05) and SOD-1 (p < 0.05) were related to three and to fivefold larger tumor sizes, respectively." (PMID 34785721, 2021). "At 6 weeks post Sod1 knockout (TAM), tumor burden in Sod1−/− KP mice was analyzed and found significantly lower than that in Sod1+/+ KP mice." (PMID 33859191, 2021). "Avastin-treated mice with the supplements, at medium and high levels, have lower expression of SOD-1 in tumor tissues than did Avastin alone." (PMID 33805447, 2021). "SOD1 expression was significantly reduced in LIHC higher-grade tumor samples as compared to the normal tissues (p < 2.319400 × 10−3)." (PMID 34203465, 2021). "This study further provides genetic evidence that SOD1 is critical for KRAS mutant NSCLC tumor development and maintenance." (PMID 33859191, 2021). "This is because the activity of superoxide dismutase 1 will decrease with the gradual development of tumor, while the activity of nitric oxide synthase will increase significantly, which further result in disordered level of OXPHOS in tumor cells." (PMID 34012953, 2021). "To evaluate the impact of NMD on PTCs across the SOD1 gene, we have analyzed experimental data from a large-scale analysis of approximately 80,000 matched tumor exomes and transcriptomes available on the cBio Cancer Genomics Portal17,18." (PMID 33244158, 2020). "Mitochondrial protein degradation increased in tumour‐bearing wild‐type mice (wild‐type saline, 0.0204 ± 0.00159; wild‐type LLC, 0.167 ± 0.00157) and tumour‐bearing Sod1KO mice (Sod1KO saline, 0.0231 ± 0.00108; Sod1 KO LLC, 0.0645 ± 0.000631)." (PMID 32918528, 2020). "The antioxidant enzyme superoxide dismutase (SOD) activity was found to be higher in the tumor as compared to its surrounding (SOD1)." (PMID 32158360, 2020). "SOD1 has high overall expression in breast tissue, and its expression is further increased in tumor tissues, whereas SOD2 and SOD3 are expressed at approximately levels twofold lower than SOD1 levels." (PMID 29478325, 2019). "In an in vitro study carried out on lung adenocarcinoma, inhibition of SOD1 alleviated the growth of KRAS-mutant tumor cells." (PMID 31766246, 2019). "The tumor growth was analyzed together with the blood levels of both oxidants (ROS) and anti-oxidants (SOD-1 and GSH)." (PMID 30669508, 2019). "This set of experiments was aimed at establishing the relationship between blood levels of GSH and SOD-1 as compared to the tumor size at the end of FPP treatment." (PMID 30669508, 2019). "The secreted CXCL1 enhanced DNA damage repair of tumor cells by inhibiting ROS-scavenging enzyme superoxide dismutase 1 (SOD1) expression." (PMID 31101063, 2019). "In fact, SOD1 inhibition using a highly specific copper-binding compound induced antiangiogenic effects, proliferation inhibition and tumour apoptotic cell death." (PMID 29360852, 2018). "The SOD1 protein level was notably increased in 17 representative tumours compared with normal tissues." (PMID 29891006, 2018). "In the case of MCF-7 cells, the increased SOD1 concentration was assigned as one of the direct mechanisms conditioning the resistance of tumor cells to DOX action." (PMID 30347787, 2018). "Of the four tumor tissue samples, only one tumor sample from a 61-year-old subject showed greater SOD1 levels, but SOD2 levels were lower than the respective healthy tissue sample." (PMID 29596499, 2018).
tumor (continued). "Our results indicate that tumor tissue has greater total protein carbonylation, lower SOD1 and SOD2 protein levels, lower total SOD activity, and higher LC3-II levels compared to adjacent healthy tissue." (PMID 29596499, 2018). "Despite the greater SOD1 protein level, total protein carbonyl level was still higher in this tumor tissue sample compared to healthy counterpart." (PMID 29596499, 2018). "Conversely, it has been also observed by several authors that SOD1 overexpression makes tumor cells resistant to oxidative stress and chemotherapy." (PMID 28770020, 2017). "Previous studies have shown that DHA inhibits tumor growth and induces apoptosis through oxidative stress, and SOD1 plays an important role in determining the cytotoxic effects of DHA on different tumor cells." (PMID 28468627, 2017). "When 500 ng/ml CXCL1 antibody or 400 nM CXCR2 inhibitor SB225002 was added into CAF medium, SOD1 was significantly upregulated in tumor cells, suggesting CAF-secreted CXCL1 inhibited the expression of SOD1." (PMID 28518141, 2017). "It has been demonstrated that enhanced level of GPx alone can prevent oxidative insult in SOD1 and catalase dual suppressed cells, thereby suggesting concordant roles of these three antioxidant enzymes in tumor progression/regression." (PMID 26682000, 2016). "On the other hand, in tumor cell lines the early increase of SOD1 and SOD2 levels was followed by a strong reduction of both protein expression after 72 hours of treatment." (PMID 27280849, 2016). "In a tumor cell line it has been proved that SOD1 counteracts stressful conditions by favoring the binding of transcriptional factors to DNA and inducing the synthesis of proteins with a protective role." (PMID 24155874, 2013). "It was suggested earlier that the levels of superoxide dismutase 1 expression plays an important role in determining the sensitivity of different tumor cells to the cytotoxic effects of DHA." (PMID 20421971, 2010). "It has been shown that ATN-224 has antiproliferative and/or proapoptotic effects on tumour cells in vitro but only when SOD1 activity was inhibited almost 100%." (PMID 18253124, 2008). "Altogether, these data indicate that SOD1 inhibition can be detected even after a single dose of ATN-224 in the tumour, plasma and blood cells, much earlier than the detection of decreases in Cp are observed in mice or humans." (PMID 18253124, 2008). "SOD1 was found to be relatively overexpressed in resistant tumours ('low' and 'mid percentage') in keeping with a proposed role in the neutralisation of free radicals, one means by which anthracyclines are thought to inflict cellular damage." (PMID 16790077, 2006). "In vivo tests revealed that CBR3-AS1 accelerated tumor development and may control the activity of the miR-409-3p target gene SOD1." (PMID 40356687, 2025). "SOD1 serves as a downstream target of the mammalian target of rapamycin complex 1 (mTORC1), and mammalian target of rapamycin (mTOR) is thought to play a key role in promoting tumor cell survival and proliferation." (PMID 40867576, 2025). "SOD1 plays a role in tumor growth in melanoma and non-small cell lung cancer." (PMID 40244057, 2025). "Importantly, this dependency creates a therapeutic vulnerability: pharmacological inhibition of antioxidant components—such as GPX4, Trx1, TrxR, and SOD1—can tip the balance toward lethal oxidative stress and selectively kill tumor cells." (PMID 40867898, 2025). "SOD1 observed to be upregulation suggests that tumor cells produce a certain protective mechanism." (PMID 39239650, 2024). "Similarly, the expression of SOD1 in non‐HBV tumours (1.12 ± 0.19) was significantly lower than in HBV‐positive tumours (4.04 ± 0.39) (p = 0.002)." (PMID 39034442, 2024). "Furthermore, the depletion of CHI3L1 significantly increased SOD1 expression in in vivo tumor and lung tissues." (PMID 37215572, 2023). "SOD1–3 are related to oxidative stress and reactive oxygen species in the tumor microenvironment." (PMID 35712475, 2022).
tumor (continued). "Moreover, SIRT5 has been proven to affect tumor development by regulating the expression levels of superoxide dismutase 1(SOD1) and citrate synthase (CS)." (PMID 36397343, 2022). "To demonstrate the interaction between DGAT1 and SOD1 on tumor growth in vivo, we have again relied on pharmacological agents that may have generated off-target effects that contributed to tumor growth inhibition." (PMID 35732120, 2022). "However, simultaneous DGAT1 and SOD1 inhibition leads to catastrophic levels of ROS accumulating in tumor cells, triggering their death." (PMID 35732120, 2022). "The functional effect of SOD1 remains controversial with specific regard to whether SOD1 overexpression prevents or induces tumor progression, especially in sorafenib-resistant HCC." (PMID 34203465, 2021). "High expression of SOD-1, Trx, and Ref-1 was determinant of the larger tumor." (PMID 34785721, 2021). "The results show that detectable amounts chromium and chlorine in the tumor tissue, as well as the occurrence of high protein expression of OGG1/2, SOD1, Ref-1 and Trx-1 may influence the tumor growth and predict the clinical evolution of OSCC." (PMID 34785721, 2021). "However, by 14 weeks post tumor initiation when adenocarcinomas were developed, Sod1−/− KP mice showed significantly less tumor burden than Sod1+/+ KP mice, suggesting that SOD1 is required for KP tumor development and/or maintenance." (PMID 33859191, 2021). "TLR9 overexpression increased HCC cell proliferation, whereas TLR9 inhibition from hydroxychloroquine (HCQ) decreased HCC cell proliferation, tumor growth, oxidative stress marker (SOD1), and the formation of autophagosome bodies (reduced ATG5 and Beclin-1 expression)." (PMID 34203465, 2021). "The impairment of rRNA processing by SOD1 knockdown in human NSCLC cells is consistent with our in vivo data in the mouse showing that SOD1 knockout attenuated NSCLC tumor growth but did not cause any apparent abnormality in normal lungs." (PMID 33859191, 2021). "High SOD1 expression can promote tumor cell proliferation through multiple mechanisms." (PMID 32391354, 2020). "Immunohistochemical analysis confirmed that high expression of SOD1 was associated with larger tumor size (p = 0.011), lymph node metastasis (p < 0.001), and advanced pTNM stage (p < 0.001) in NSCLC." (PMID 32391354, 2020). "The rise in the expression of cytosolic SOD1 levels may have been a response to counterbalance the deleterious effects of increased oxidative stress in the tumor cells as previously suggested." (PMID 31487876, 2019). "With regard to tumor subgroups, it is plausible that SOD1 inhibition might be especially effective in tumors with an intact mTORC1 sensor, i.e. tumors that effectively downregulate mTORC1 signaling in response to hypoxia and/or nutrient deprivation or in combination with mTORC1 inhibitors." (PMID 39187509, 2024). "Interestingly, however, when measured in two outers and two inner tumour quadrants, we observed inhomogenous and fluctuating SOD1 mRNA expression levels between the respective quadrants, that we mechanistically validated on the protein levels in an independent study (unpublished observation)." (PMID 37582934, 2023). "Substantial progress has been made in determining the function of SOD1 in modulating tumor cell proliferation and metastasis, however, little is known about how and which transcription factors (including miRNAs or long non-coding RNAs) could regulate SOD1 gene transcription or translation." (PMID 32391354, 2020). "Furthermore, we tested whether RNAi can prevent the tumor-like growth in the presence of overexpressed ROS scavengers, which include superoxide dismutase 1 (SOD1), SOD2 and catalase." (PMID 33199523, 2020).